ADCY6 (adenylate cyclase 6)
Description:
Catalyzes the formation of the signaling molecule cAMP downstream of G protein-coupled receptors. Functions in signaling cascades downstream of beta-adrenergic receptors in the heart and in vascular smooth muscle cells. Functions in signaling cascades downstream of the vasopressin receptor in the kidney and has a role in renal water reabsorption. Functions in signaling cascades downstream of PTH1R and plays a role in regulating renal phosphate excretion. Functions in signaling cascades downstream of the VIP and SCT receptors in pancreas and contributes to the regulation of pancreatic amylase and fluid secretion (By similarity). Signaling mediates cAMP-dependent activation of protein kinase PKA. This promotes increased phosphorylation of various proteins, including AKT. Plays a role in regulating cardiac sarcoplasmic reticulum Ca(2+) uptake and storage, and is required for normal heart ventricular contractibility. May contribute to normal heart function (By similarity). Mediates vasodilatation after activation of beta-adrenergic receptors by isoproterenol. Contributes to bone cell responses to mechanical stimuli (By similarity).
Synonyms: AC6; LCCS8
Tractability: Antibody: UniProt places it where antibodies can reach, with high confidence; its Gene Ontology location is reachable by antibodies, with high confidence; UniProt predicts a signal peptide or a membrane-spanning region. PROTAC: ubiquitination databases record sites on it; its protein half-life has been measured; a small molecule that binds it is known.
Gene: Protein-coding gene on chromosome 12 (48,766,191 to 48,789,906, reverse strand). Ensembl gene ENSG00000174233.
Subcellular location: Cell membrane; Cell projection, cilium; Cell projection, stereocilium
Subcellular location (Human Protein Atlas): Golgi apparatus
Pathways (Reactome):
Signal Transduction: Adenylate cyclase activating pathway; G alpha (i) signalling events; G alpha (s) signalling events; G alpha (z) signalling events; GPER1 signaling; Hedgehog 'off' state; PKA activation
Metabolism: Adrenaline,noradrenaline inhibits insulin secretion; Glucagon signaling in metabolic regulation; Glucagon-like Peptide-1 (GLP1) regulates insulin secretion; PKA activation in glucagon signalling
Disease: ADORA2B mediated anti-inflammatory cytokines production; FCGR3A-mediated IL10 synthesis
Cellular responses to stimuli: High laminar flow shear stress activates signaling by PIEZO1 and PECAM1:CDH5:KDR in endothelial cells
Neuronal System: Adenylate cyclase inhibitory pathway
Transport of small molecules: Vasopressin regulates renal water homeostasis via Aquaporins
Gene Ontology:
Molecular function: adenylate cyclase activity; protein binding; protein kinase C binding; protein kinase binding; phosphorus-oxygen lyase activity
Biological process: adenylate cyclase-activating dopamine receptor signaling pathway; adenylate cyclase-activating G protein-coupled receptor signaling pathway; adenylate cyclase-activating serotonin receptor signaling pathway; blood vessel diameter maintenance; cAMP biosynthetic process; cellular response to catecholamine stimulus; cellular response to forskolin; cellular response to prostaglandin E stimulus; adenylate cyclase-inhibiting G protein-coupled receptor signaling pathway; adenylate cyclase-inhibiting serotonin receptor signaling pathway; cellular response to glucagon stimulus; cellular response to vasopressin; negative regulation of neuron projection development; negative regulation of urine volume; renal water homeostasis; vascular endothelial cell response to laminar fluid shear stress; cyclic nucleotide biosynthetic process; intracellular signal transduction; system process
Cellular component: plasma membrane; membrane; cilium; stereocilium
Genetic constraint (gnomAD): Loss-of-function variants: 59 observed, 114.75 expected, observed/expected ratio (o/e) 0.51, 90% interval 0.42 to 0.64. The upper end of that interval is the gene's LOEUF score, 0.64, which puts it in group 2 of 6, group 1 being the genes least tolerant of losing a copy. Missense variants: 1,242 observed, 1,645.7 expected, observed/expected ratio (o/e) 0.75, 90% interval 0.72 to 0.79. Synonymous variants: 576 observed, 668.25 expected, observed/expected ratio (o/e) 0.86, 90% interval 0.8 to 0.92.
Homologues: Orthologues: chimpanzee ADCY6 (99% identical), macaque ADCY6 (99% identical), pig ADCY6 (96% identical), guinea pig ADCY6 (95% identical), mouse Adcy6 (94% identical), rat Adcy6 (94% identical), rabbit ADCY6 (91% identical), dog ADCY6 (86% identical), tropical clawed frog adcy6 (75% identical), zebrafish adcy6a (73% identical), zebrafish adcy6b (72% identical). Paralogues in human: ADCY5 (69% identical), ADCY1 (39% identical), ADCY8 (38% identical), ADCY2 (36% identical), ADCY4 (34% identical), ADCY7 (34% identical), ADCY3 (33% identical), ADCY9 (27% identical), GUCY2D (16% identical), GUCY2F (16% identical), NPR2 (15% identical), NPR1 (14% identical), and 5 more.
Diseases named in the same sentence as ADCY6 in open-access papers:
ADCY6 is named in the same sentence as 44 diseases in open-access papers, as found by Europe PMC text mining. Sharing a sentence is not in itself a finding about the gene and the disease. The quoted sentences say what the papers report.
heart failure (10 papers, 2012 to 2025). Inability of the heart to pump blood at an adequate rate to meet tissue metabolic requirements. "Circ-HIPK3 interacts with miR-17-3p to elevate ADCY6 expression, thereby strengthening adrenaline-mediated effects in heart failure." (PMID 36800233, 2023). "Circ-HIPK3, for example, exacerbates the effect of adrenaline on heart failure through modulating the miR-17-3p/ADCY6 axis." (PMID 36800233, 2023). "Gene therapies targeting Adenylyl cyclase 6 (ADCY6) promoted left ventricular ejection fraction at week 4 in symptomatic heart failure patients." (PMID 36507276, 2022).
cardiomyopathy (7 papers, 2015 to 2025). A disease of the heart muscle or myocardium proper. "It is worth noting that the combination of the heterozygous variants in CAP2, ADCY6, and SYNE2, associated with the loss of function in TPM2, could also be related to cardiomyopathy." (PMID 37744435, 2023).
breast cancer (6 papers, 2019 to 2025). A primary or metastatic malignant neoplasm involving the breast. "An association is observed between downregulated ADCY6 gene expression and hypomethylation with a better prognosis in breast cancer patients." (PMID 35832555, 2022). "In this study, the roles of ADCY6 in breast cancer were systematically investigated, and the mechanism underlying these effects was also explored." (PMID 35978806, 2022). "Association of ADCY6 expression with clinicopathological characteristics in Breast Cancer." (PMID 35978806, 2022). "Furthermore, ADCY6 may be implicated in breast cancer progression and affect breast cancer prognosis through calcium-regulated immune and molecular signaling pathways." (PMID 35832555, 2022). "At the same time, TET1 affects the expression of ADCY6 by removing DNA methylation, thereby regulating the malignant progression of breast cancer." (PMID 39823268, 2025). "In luminal-like breast cancer, ADCY6 is modified by DNA methylation, and patients with low methylation and high expression have a better prognosis." (PMID 35978806, 2022). "More importantly, bioinformatics analysis showed that TET1 is regulated by miR-27a-3p and regulates the methylation of ADCY6 to affect the EMT process of breast cancer cells, thereby affecting the malignant biological behaviour of breast cancer." (PMID 35978806, 2022). "miR-27a-3p negatively regulates the expression of TET1 and affects the EMT process of breast cancer through ADCY6, thereby promoting the malignant biological behaviour of breast cancer." (PMID 35978806, 2022). "Immunoblotting suggested that ADCY6 was expressed at low levels in breast cancer tissues, and mainly expressed in the cytoplasm of breast cancer cells." (PMID 35978806, 2022). "We found that ADCY6 is expressed at low levels in breast cancer and leads to increases in the proliferation, invasion and migration of breast cancer cells." (PMID 35978806, 2022). "Currently, many studies have focused on demonstrating the abnormal expression of ADCY6 in various cancers, including breast cancer." (PMID 35978806, 2022). "For the first time, this study demonstrates that TET1 increases the expression of ADCY6 through demethylation, and inhibits the progression of malignant biological behaviour of breast cancer by inhibiting EMT signaling pathway." (PMID 35978806, 2022). "More importantly, the increase in ADCY6 reversed the promoting effect of miR-27a-3p overexpression on the malignant biological behaviour of breast cancer cells and reduced the expression of EMT-related proteins that had been increased by miR-27a-3p." (PMID 35978806, 2022). "Using lentiviral stable miRNA transfection together with cell biology functional assays and gene expression/target analysis, we investigated the interaction between miR-27a-3p, TET1 and ADCY6 in breast cancer." (PMID 35978806, 2022). "Overall, these results demonstrated that miR-27a-3p binds to TET1 and downregulates TET1 to activate EMT by promoting DNA methylation of ADCY6, thus promoting proliferation, migration and invasion of breast cancer cells." (PMID 35978806, 2022). "Our research demonstrates that TET1 is expressed at low levels in breast cancer, leading to the low demethylation of ADCY6, inhibiting ADCY6 protein expression, and regulating the malignant biological behaviour of breast cancer through EMT signalling pathway." (PMID 35978806, 2022). "In breast cancer, ADCY6 has been reported to aberrantly regulate DNA methylation, leading to the malignant growth of breast cancer." (PMID 35978806, 2022). "Determining whether there is DNA methylation transferase in breast cancer also plays an important role in regulating ADCY6 DNA methylation is an important direction for future research." (PMID 35978806, 2022). "Unsurprisingly, the expression of ADCY6 was also lower in breast cancer cells." (PMID 35978806, 2022). "qRT–PCR results showed that ADCY6 was expressed at low levels in breast cancer tissues." (PMID 35978806, 2022).
breast cancer (continued). "More importantly, high ADCY6 expression and low methylation in breast cancer patients is correlated with better prognosis, and the activation of signalling pathways, immune checkpoint receptors and ligands related to the immune process is negatively correlated." (PMID 35978806, 2022). "Based on the results of in vivo and in vitro experiments, we further analysed whether miR-27a-3p and ADCY6 affect the malignant biological behaviour of breast cancer by regulating EMT." (PMID 35978806, 2022). "In addition, WB results also confirmed the protein expression of ADCY6 was lower in breast cancer tissues than in paired normal adjacent tissues." (PMID 35978806, 2022). "Increasing the expression of TET1 could inhibit the malignant biological behaviour of breast cancer cells and suggests that the high methylation level of ADCY6 is due to the low TET1 expression in breast cancer." (PMID 35978806, 2022). "This study demonstrates that ADCY6 functions as a tumor suppressor gene in breast cancer." (PMID 35978806, 2022). "Bioinformatics and clinical data were used to analyse the expression of ADCY6 in breast cancer." (PMID 35978806, 2022). "The results showed that the methylation of ADCY6 was high in breast cancer." (PMID 35978806, 2022). "Hence, increasing the expression of ADCY6 could inhibit proliferation of breast cancer cells." (PMID 35978806, 2022). "In conclusion, our study demonstrates that TET1, which is negatively regulated by miR-27a-3p, functions as a key enzyme of DNA demethylation for ADCY6 and thereby leads to EMT and regulates malignant biological behaviour of breast cancer." (PMID 35978806, 2022).
myocardial hypertrophy (5 papers, 2016 to 2025). "Our findings show that upregulation of miR-182 is associated with angiogenesis-induced myocardial hypertrophy and decreases the expression of branched chain aminotransferase 2 (Bcat2), forkhead box O3 (Foxo3), and adenylate cyclase type 6 (Adcy6)." (PMID 26888314, 2016).
myocardial infarction (3 papers, 2016 to 2024). Gross necrosis of the myocardium, as a result of interruption of the blood supply to the area, as in coronary thrombosis. "In our study, we found that circ-HIPK3 can be upregulated significantly in heart post myocardial infarction (MI) and affected the Ca2+ in cytoplasm via circ-HIPK3 - miR-17-3p - ADCY6 axis." (PMID 31595165, 2019).
acute myeloid leukemia (1 paper, 2021). Acute myeloid leukemia (AML) is a group of neoplasms arising from precursor cells committed to the myeloid cell-line differentiation. "We used UALCAN to analyze GPSM1-related genes in the LAML dataset for acute myeloid leukemia, and the correlation analysis results showed that GPSM1 was positively correlated with ADCY6." (PMID 34257610, 2021).
arthrogryposis multiplex congenita (1 paper, 2023). Arthrogryposis multiplex congenita (AMC) is a group of disorders characterized by congenital limb contractures. "Mutations in the ADCY6 gene were found to cause abnormal peripheral axon myelination and lethal arthrogryposis multiplex congenita in humans." (PMID 37127773, 2023). "Four ADCY6 mutations have been shown to cause lethal arthrogryposis multiplex congenita in humans." (PMID 37127773, 2023).
dilated cardiomyopathy (1 paper, 2018). Cardiomyopathy which is characterized by dilation and contractile dysfunction of the left and right ventricles. "KEGG pathway analysis on cardiac loop genes reveals enrichments for terms, such as dilated cardiomyopathy, vasopressin-regulated water reabsorption, and hypertrophic cardiomyopathy (the genes within these terms include: Adcy6, Aqp3, Creb3l4, Des, Itgb5, Itga9, Myl2, Myl3, and Stx4a)." (PMID 30697540, 2018).
gastric cancer (1 paper, 2019). A primary or metastatic malignant neoplasm involving the stomach. "Upregulation of ADCY6 activates the CREB pathway by increasing the tumorigenic potential of cells reported in gastric cancer." (PMID 31635135, 2019).
Glucose intolerance (1 paper, 2025). Glucose intolerance (GI) can be defined as dysglycemia that comprises both prediabetes and diabetes. "Upregulation of ADCY6 is associated with increased hepatic glucose production, which can contribute to high blood glucose and overall glucose intolerance." (PMID 40316897, 2025).
insomnia (1 paper, 2018). A sleep disorder characterized by difficulty in falling asleep and/or remaining asleep. "Further, in depressed subjects with late insomnia, genetic variants have been found in the precursor miR-182, which may inhibit Adenylate Cyclase 6 (ADCY6), CLOCK and DSIP (also known as TSC22 Domain Family Member 3) expression." (PMID 29535611, 2018).
lung carcinoma (1 paper, 2017). "Six genes showed particularly stronger expression pattern in lung cancer tissues, as compared to normal lungs, which demonstrated that these six genes (GABBR1, PDE4B, PDE4C, ADCY6, ADCY1 and GIPR) had more likelihood of being direct targets of miR-542-5p in lung cancers." (PMID 28927388, 2017).
metabolic syndrome (1 paper, 2019). A cluster of metabolic risk factors for CARDIOVASCULAR DISEASES and TYPE 2 DIABETES MELLITUS. "Finally, eleven CpG sites were associated with metabolic syndrome: cg08862778 (MTOR), cg11322849 (INS), cg07199894 (ULK1), cg11658986-cg04149773 (ADCY6), cg14862787-11301281 (CREB5), cg14844401-cg20300093 (ADCY5), cg01284192 (IGF1R) and cg08128650 (RELA)." (PMID 30926763, 2019).
overnutrition (1 paper, 2024). An imbalanced nutritional status resulting from excessive intake of nutrients. "Notably, the upregulated gene ADCY6 also formed crucial interactions, suggesting a compensatory mechanism in response to overnutrition." (PMID 39375502, 2024).
cancer (8 papers, 2017 to 2024). A tumor composed of atypical neoplastic, often pleomorphic cells that invade other tissues. "Researchers have found evidence that ADCY6 expression is aberrant in tumor tissues and cancer cells." (PMID 38419894, 2024). "Because ADCY6 is a promising target in cancer therapy, it is important to know how it relates to other excretory genes." (PMID 38132440, 2023). "Some researchers reported the involvement of ADCY6 in the cellular processes related to the cancer phenotype like cell cycle, apoptosis, DNA repair, protease inhibition, proteolysis, and transcriptional regulation." (PMID 35832555, 2022). "Therefore, for this patient, manipulating the expression of ADCY6 would have different effects on his cancer nodules." (PMID 38132440, 2023). "Therefore, most of the existing studies focus on the abnormal expression and dysfunction of ADCY6 in different malignant tumor tissues." (PMID 35978806, 2022). "An increasing number of researchers have studied the role of ADCY6 in cancer." (PMID 35978806, 2022). "The importance of immunotherapy and targeted therapies has become growing in cancer treatment, and the anticancer therapies targeting the ADCY family, certainly ADCY1 and ADCY6, are becoming increasingly possible." (PMID 35832555, 2022). "The comparison of mRNA levels of ADCY6 and ADCY7 in normoxic versus hypoxic samples revealed their increased hypoxic transcription in all four cancer cell types, whereas ADCY3 was unchanged or reduced." (PMID 28860539, 2017). "In laryngeal cancer, ADCY6 is a biomarker with significantly different expressions in cancer and noncancer samples." (PMID 35832555, 2022). "The increased overall correlation of the ADCY6 and AP2A1 with all other genes from the “Endocrine and other factor-regulated calcium reabsorption” pathway in PTA, but the decrease in the other two cancer nodules, indicates substantially different gene networks." (PMID 38132440, 2023).
tumor (6 papers, 2017 to 2024). "Increased tumor development, invasion, and metastasis have all been linked to elevated ADCY6 levels." (PMID 38419894, 2024). "The present study demonstrates that GPSM1 promotes tumor growth in BALL-1 and Reh cells by modulating ADCY6-RAPGEF3-JNK signaling." (PMID 34257610, 2021). "The hub gene ADCY6, CXCL3, NPBWR1, TAS2R38, and PTGDR2 highly influence the clinical traits of age, histology types, neoplasm histologic grade, and overall survival in ESCA and READ, leading to their similarity in these clinical traits." (PMID 33552958, 2020). "Several of the understudied genes are directly involved in critical metabolic pathways of tumor etiology, including glucose metabolism (SORD), lipid biosynthesis (FAR1), cAMP signaling pathway (PDE7A, ADCY6), and glutamate anaplerosis (ABAT, GLUD1)." (PMID 31231467, 2019).
adenocarcinoma (1 paper, 2013). A common cancer characterized by the presence of malignant glandular cells. "Another notable differential interaction selected by BNKL is GNAS→ADCY6 (activation in adenocarcinoma and suppression in SQCC) while, according to KEGG, in normal cells we have a stimulating effect of GNAS, the gene encoding the G-protein, on ADCY6." (PMID 24565081, 2013).
ADCY6 also shares sentences with these, for which no sentence is quoted: cardiovascular diseases (3 papers); cyst (3); heart disease (2); Myocardial fibrosis (2); neurodegenerative disease (2); Abdominal obesity (1); acute lymphoblastic leukemia (1); Anxiety (1); autosomal dominant polycystic kidney disease (1); bladder cancer (1); bone metabolism disorder (1); congestive heart failure (1); diabetes (1); female infertility (1); Hypercholesterolemia (1); hypertrophic cardiomyopathy (1); hypothyroidism (1); Insulin resistance (1); Kidney Cyst (1); nephrogenic diabetes insipidus (1); neuropathies (1); Obesity (1); osteosarcoma (1); pancreatic ductal adenocarcinoma (1); prostate adenocarcinoma (1); Usher syndrome (1); uveitis (1).